CHEK2 (checkpoint kinase 2)
Diseases named in the same sentence as CHEK2 in open-access papers (continued):
Sharing a sentence is not in itself a finding about the gene and the disease.
breast cancer (continued). "Most women with breast cancers had panel testing, allowing extrapolation of likely frequencies of other common familial genes (ATM, CHEK2, PALB2)." (PMID 34312777, 2021). "Thus, none was suggested to be a modifier of breast cancer risk in CHEK2:c.1100delC carriers." (PMID 34285278, 2021). "Histological analyses of breast cancer subtypes showed that there were varying trends between ATM and CHEK2." (PMID 35008774, 2021). "Collectively, our study is the first to document the oncogenetic role of PRR14 in breast cancer, which protects cells from apoptosis and stimulates proliferation by activating the PI3-kinase/Akt/mTOR pathway and inhibiting the CHEK2 pathway." (PMID 32541902, 2020). "Among Polish women who carry a truncating CHEK2 mutation without a family history of breast cancer, the risk increase is about three-fold, and the risk is higher (increased about five-fold) in carriers of a truncating mutation of CHEK2 in the presence of positive family history of breast cancer." (PMID 32824581, 2020). "In correspondence, CHEK2 and PRR14 show opposite impact on breast cancer patients receiving chemotherapy." (PMID 32541902, 2020). "The odds ratios for breast cancer diagnosed at age 40 or below were 28.8 for BRCA1 (95% CI 18.6–44.5); 3.8 for CHEK2 (95% CI 2.5–5.5); and 3.6 for PALB2 (95% CI 1.6–7.5), and all were statistically significant." (PMID 32824581, 2020). "We check the expression of CHEK2 and PRR14 in the tumors from our previous xenograft experiment and human breast cancer samples." (PMID 32541902, 2020). "The National Comprehensive Cancer Network (NCCN) guidelines for genetic assessment in hereditary breast cancer (version 3.2019) recommends genetic evaluation of ATM, CDH1, CHEK2, NBN, NF1, and PALB2 in addition to BRCA1/2 genes." (PMID 31658756, 2019). "For example, breast cancer screening is recommended for BRCA1/BRCA2-positive men, beginning at age 35, and increased colon surveillance is recommended for CHEK2-positive individuals." (PMID 28008555, 2017). "Pathogenic variants were identified in 11.8% (6/51) of male patients with breast cancer and were found in BRCA1, BRCA2, CHEK2, and PALB2; one man was positive for both a BRCA1 and CHEK2 variant." (PMID 26681312, 2016). "Copy number losses on chromosome 22 (including the CHEK2 locus) are found in half of the CHEK2*1100delC breast cancers, of which 4 showed LOH at the CHEK2 locus." (PMID 26553136, 2015). "By unsupervised hierarchical clustering of copy number data we observed a great degree of heterogeneity amongst the CHEK2*1100delC breast cancers, comparable to the BRCAX breast cancers." (PMID 26553136, 2015). "Supervised class comparison of the copy number profiles of low TIL CHEK2*1100delC (n = 14) and BRCAX (n = 34) breast cancers identified a small number of genomic regions with differential CNAs." (PMID 26553136, 2015). "In this study we have performed high-resolution copy number, LOH and gene expression profiling of 120 familial breast carcinomas selected from a larger cohort of 155 familial breast tumors, including BRCA1, BRCA2 and CHEK2 mutant tumors." (PMID 26553136, 2015). "We performed high-resolution SNP array and gene expression profiling of 120 familial breast carcinomas selected from a larger cohort of 155 familial breast tumors, including BRCA1, BRCA2, and CHEK2 mutant tumors." (PMID 26553136, 2015).
breast cancer (continued). "Here, we describe an Italian family with a high number of cases of breast cancer and other types of tumour subjected to the MLPA test to verify the presence of BRCA1, BRCA2 and CHEK2 deletions and duplications." (PMID 24986639, 2014). "However, the p27 genotype did not modify the risk of breast cancer among CHEK2 carriers." (PMID 19401704, 2009). "Many of the known hereditary breast cancer genes such as BRCA1, BRCA2, CHEK2, ATM, and FANCJ/BRIP1 work together in a DNA repair pathway, raising the possibility that other genes in this pathway also predispose to breast cancer." (PMID 18053174, 2007). "We performed a comprehensive haplotype analysis of the ATM, CHEK2 and ERBB2 genes in a Swedish population-based study, which included 1,579 breast cancer cases and 1,516 controls." (PMID 17132159, 2006). "However, the low frequency of this alteration in our material implies that development of metachronous breast cancer and colorectal cancer in women is per se not alone to identify individuals with a high likelihood of being carriers of the CHEK2 1100delC mutation." (PMID 16539695, 2006). "Our study of index cases from multiple-case breast cancer families included 152 who had first-, second- or third-degree relatives with colorectal cancer, as well as seven with male relatives affected with breast cancer, but the CHEK2 variant was not identified in any of these index cases." (PMID 15700044, 2005). "In summary, postmenopausal carriers of PVs in BRCA1/2, ATM, CHEK2, and PALB2 are unlikely to have substantial (twofold or greater) elevations in the risk of developing breast cancer due to reproductive and lifestyle exposures." (PMID 40298171, 2025). "Our current analysis is the first study on recurrent diseases and distant diseases specifically in ER-positive breast cancer patients, showing no worse outcome for CHEK2 c.1100delC breast cancer patients compared to non-carriers." (PMID 41314031, 2025). "BRCA1/2, ATM, CHEK2, and PALB2 PV carriers do not have breast cancer OR ≥2.0 with many established risk factors." (PMID 40298171, 2025). "Most studies compared the prognosis of CHEK2 c.1100delC (also) with sporadic breast cancer patients, rather than with exclusively familial breast cancer patients." (PMID 41314031, 2025). "Heritable breast cancer (BC) is influenced by well-known high-penetrance genes such as BRCA1, BRCA2, PALB2, and CHEK2, but the contribution of many moderate- and low-penetrance genes remains unclear." (PMID 41463216, 2025). "In 2 out of 6 patients with P/LP CHEK2 or BRCA2 variants, family history included breast cancer, but none met the current guidelines for genetic testing." (PMID 38415346, 2024). "Recent molecular studies on breast cancers occurring in individuals who are heterozygous for gPVs in CHEK2 suggest that these cancers do not present with genomic instability features indictive of HRD." (PMID 38848470, 2024). "While this variant is prevalent in the Netherlands (1% in the general population), knowledge of aetiology and prognosis of breast cancer and other tumours in CHEK2 c.1100delC carriers is lacking." (PMID 39384226, 2024). "We compared our findings to breast (n = 3) and non-breast cancers (n = 25) from individuals heterozygous for CHEK2 gPVs and to breast (n = 7) and non-breast cancers (n = 21) from individuals heterozygous for BRCA1/2 gPVs." (PMID 38848470, 2024). "This individual had no documented family history of breast cancer, history of hormone treatments, BRCA1, BRCA2, PALB2 or CHEK2 P/LP variants or other explanation on chart review." (PMID 39802765, 2024). "We have also demonstrated that variation in ATM and CHEK2 does not contribute significantly to breast cancer in Orcadians." (PMID 39438716, 2024). "While DVs of ATM, CHEK2, and PALB2 have been linked to breast cancer, the additional risk conferred is not as well understood, especially among individuals with non-European ancestries." (PMID 38760335, 2024).
breast cancer (continued). "Another CHEK2 missense GPV, c.1283C>T (p.Ser428Phe), herein referred to as “S428F”, is established to also confer lower breast cancer risks, with a previously reported odds ratio of 1.26 (95% CI 0.76–2.12; p = 0.37), consistent with estimates from other studies." (PMID 39062660, 2024). "Two recent large case control studies CARRIERS in the USA3 and BRIDGES mainly in Europe4 identified six additional genes with actionable increased risks of breast cancer with ORs of around twofold to threefold (RAD51C, RAD51D, BARD1, ATM, CHEK2) and one at fourfold to fivefold (PALB2)." (PMID 38609177, 2024). "Among breast cancer patients the most prevalent occur in BRCA2, CHEK2, BRCA1 and ATM." (PMID 37790698, 2023). "In patients who are found not to carry a founder mutation, we perform full sequencing using gene panels including BRCA1, BRCA2, CHEK2, and PALB2 in breast cancer cases with familial clustering of this cancer and/or in patients with early onset disease (diagnosed at age 45 or below)." (PMID 37510234, 2023). "Furthermore, having a family member with breast cancer can increase the chance of developing prostate cancer due to their genetic makeup (e.g., BRCA1, BRCA2, HOXB13, CHEK2, HOXB13 and ATM)." (PMID 37893854, 2023). "Unlike mutations in ATM or CHEK2, mutations in ATR alone are uncommon in both primary and metastatic ER+/HER2− breast cancer." (PMID 37390209, 2023). "As expected by the global frequency, other non-BRCA genes related to hereditary breast cancer variants were found (PALB2 and CHEK2)." (PMID 36833268, 2023). "A total of 3.6% of patients carried a pathogenic/likely pathogenic variant in a known breast cancer susceptibility gene: 1.2% in BRCA1, 0.6% in each of BRCA2, ATM, CHEK2 and PALB, none of whom had any family history of breast cancer." (PMID 35039564, 2022). "In Poland, 20 founder mutations in BRCA1, BRCA2, CHEK2, PALB2, NBN, RECQL are responsible for the majority of hereditary breast cancer cases in women, but the utility this genes panel has not been tested in men." (PMID 34461861, 2021). "Among the 28 CHEK2 carriers, there were 3 patients homozygous for rs16897117, whereas among the non-carrier breast cancer cases or healthy controls, there were no rs16897117 homozygotes." (PMID 34285278, 2021). "Interestingly, some genes involved in these processes and signal pathways, such as CCNB1, CDK1, CHEK2, and MYBL2, have been widely reported as oncogenes and used in the clinical diagnosis for breast cancer patients." (PMID 34646403, 2021). "Histopathological characteristics and clinical outcomes of breast cancer patients who are CHEK2 carriers have not been thoroughly investigated." (PMID 33925588, 2021). "We note that some of these genes (e.g. CHEK2 [c.1100delC]) are not typically associated with TNBC, but are commonly included in breast cancer panels in Australia." (PMID 33637119, 2021). "CHEK2 c.1100delC carriers have shorter breast cancer-specific survival compared with non-carriers and have a higher risk of contralateral breast cancer." (PMID 33803639, 2021). "CHEK2 PV carriers were more often diagnosed with bilateral breast cancer than non-carriers (24.5% versus 15.2%), but the difference was not statistically significant." (PMID 33468213, 2021). "None of the CHEK2 carriers or the familial breast cancer patients were found to be homozygous for the rs16897117 variant." (PMID 34285278, 2021).
breast cancer (continued). "Our results suggest that breast cancers among carriers of PVs in ATM and CHEK2, which are relatively common and more typically ER/PR-positive, may behave similarly to those of women testing negative for germline PVs." (PMID 33426465, 2021). "As there were no cases of lobular invasive breast cancer among the 31 biallelic CHEK2 PV carriers, it was not possible to determine an overall odds ratio (OR) for developing any type of breast cancer (lobular invasive, ductal invasive, and DCIS)." (PMID 31993860, 2020). "BRCA1 and BRCA2 germline pathogenic variants were found in 7.3% of the IBC patients, 6.3% had a mutation in other cancer genes (PALB2, CHEK2, ATM and BARD1), and 1.6% had a germline pathogenic variant in other genes not related with breast cancer." (PMID 32075053, 2020). "It is interesting that heterozygous mutations in other genes in this pathway (i.e., BRCA1, BRCA2, CHEK2, NBN, ATM) predispose to breast cancer, but a heterozygous mutation in BLM does not appear to be pathogenic for breast cancer." (PMID 31614901, 2019). "Three genes with evidence for association with breast cancer are on the eMERGEseq platform (ATM, CHEK2, PALB2), but were not used to develop outcomes." (PMID 30011878, 2018). "In a previous Finnish study, the CHEK2 c.1100delC mutation frequency was not significantly elevated in MBC patients, and did not seem to affect the age on breast cancer onset." (PMID 28874143, 2017). "Carriers of deleterious variants in either ATM, CHEK2, PALB2 or NBN are typically counseled for their risk of breast cancer, but not ovarian cancer risk despite associations in current literature." (PMID 28591191, 2017). "We and others have reported that the breast cancer risk fraction contributed by missense variants in BRCA1, BRCA2, ATM and CHEK2 is as high, if not higher, than protein-truncating variants in these genes." (PMID 27099641, 2016). "The moderate-risk genes—CHEK2, ATM, and PALB2—had positive yields of 2.0% (n = 66), 1.0% (n = 33), and 0.8% (n = 25), respectively, among the 3,315 women with breast cancer and no previous testing." (PMID 26681312, 2016). "In conclusion, in contrast to basal-like BRCA1 mutated breast cancers, no apparent specific somatic copy number aberration (CNA) profile for CHEK2*1100delC breast cancers was found." (PMID 26553136, 2015).
breast cancer (continued). "Furthermore, copy number aberrations were mostly seen at low frequencies in both the CHEK2*1100delC and BRCAX group of breast cancers." (PMID 26553136, 2015). "Four known biomarkers (CHEK2 in both plasma and urine, CDKN1B, PCNA, and THBS1) were identified as false positives (red) in our breast cancer list, and seven (KRAS, GDNF in both breastmilk and plasma, MYCL1 in both blood and serum, CD40LG, CGA, CTAG1A, ERCC6, and HRAS) in our lung cancer list." (PMID 25379168, 2014). "Four PALB2 p.Q775X positive cases were also identified in a subsequent study involving 564 (0.7%) breast cancer cases not selected for family history of cancer, which also showed that 6% of cases harbored common BRCA1, BRCA2 or CHEK2 mutations." (PMID 23302520, 2013). "In this study, we screened the whole CHEK2 coding sequence for mutations in non-BRCA HBC families and a control population without any family history of breast cancer." (PMID 22114986, 2011). "The OR that we observed for T+SJVs is numerically somewhat higher than that reported in the 2004 CHEK2 Breast Cancer Case-Control Consortium study of c.1100delC, but not significantly, as our 95% CIs do include the point estimate from that study." (PMID 21244692, 2011). "A similar idea seems to have guided an investigation of the CHEK2 gene in breast cancer that was carried out using non-carriers of BRCA1 or BRCA2 mutations." (PMID 21187953, 2010). "The results indicate that common variation in the ATM, CHEK2 or ERBB2 genes does not have a role in breast cancer aetiology or progression." (PMID 17132159, 2006). "However, no consensus was reached for recontact regarding breast cancer risk management in intermediate penetrance CSGs (ATM, CHEK2, RAD51C, RAD51D or BARD1)." (PMID 41159931, 2025). "We don’t observe significant differences in the allele frequencies between different regions of Poland, i.e., for BRCA1, PALB2, CHEK2, NBN, RECQL, and also for the GEN1 founder p.Lys645Cysfs*29 variant, neither in breast cancer cases nor in controls (for GEN1 data)." (PMID 40649769, 2025). "In CHEK2-1100delC carriers, the risk of breast cancer did not change in women also carrying P/LP variants in BRCA1, possibly because CHEK2 and BRCA1 may function in the same biological pathway." (PMID 39858629, 2025). "There are limited prospective data on whether established risk factors modify breast cancer risk in women with pathogenic variants (PV) in BRCA1/2 and virtually no risk modification data for ATM, CHEK2, or PALB2." (PMID 40298171, 2025). "Moreover, rates of risk-reducing salpingo-oophorectomy were similar for females with an 1100delC and I157T GPV, both with and without a breast cancer diagnosis, suggesting possible over-treatment among CHEK2 carriers." (PMID 39062660, 2024). "Depending on their family history of breast cancer, women from CHEK2 families who tested negative themselves might still be eligible for additional breast cancer surveillance." (PMID 39384226, 2024).